AHR (aryl hydrocarbon receptor)
Diseases named in the same sentence as AHR in open-access papers (continued):
Sharing a sentence is not in itself a finding about the gene and the disease.
tumor (continued). "Exogenous KYN reversed the neuroprotective effect, and the neurotoxic effect of KYN was shown to be mediated by the activation of the aryl-hydrocarbon receptor (AhR), as KYN is an endogenous ligand of this transcription factor involved in tumor cell progression and in promoting neuronal cell death." (PMID 37833970, 2023). "By thus generating derivatives of tryptophan that activate AHR, IL4I1 may have a role to play in anti-inflammatory responses, as well as in a tumor escape mechanism that reduces survival in cancer patients." (PMID 35295226, 2022). "Finally, the combination of AhR inhibitor and EGFR TKIs showed a significant suppressive effect on tumor growth and reversed the EGFR TKIs resistance." (PMID 35831824, 2022). "Preclinical studies demonstrated that IFN-γ resulting IDO1/aryl hydrocarbon receptor (AhR) dependent p27 induction could prevent STAT1 signaling, thus suppressing the process of tumor cell death and activating tumor dormancy program." (PMID 36032151, 2022). "Further analyses of the skin lesions did not reveal any obvious genotype-specific differences in tumor histology/biochemistry, indicating that, in the context of photocarcinogenesis, AHR activity mainly affects the tumor initiation phase." (PMID 35311158, 2022). "Moreover, kynurenine produced by tumor cells induces PD-1 expression in human and mouse CD8+ T cells through nuclear translocation of the receptor AhR." (PMID 36713558, 2022). "Mechanistically, tumor cell–derived FGF-2 strongly promoted pericyte proliferation and pericyte-specific expression of an orphan chemokine (C-X-C motif) ligand 14 (CXCL14) via FGFR1/AHR signaling." (PMID 35439170, 2022). "Additionally, AHR, DDA1, and UBE4B protein were detected in all tissue samples analyzed from an additional cohort of brain metastases independently of primary tumor source and the presence of clinically validated HSP90‐dependent oncogenes (Table EV5)." (PMID 35174975, 2022). "Therefore, understanding these crosstalks between immune system, tumor progression and gut microbiota is of utmost importance to adapt immunomodulatory drugs, such as ICI and drugs targeting the Trp-Kyn-AhR axis." (PMID 35173722, 2022). "Therefore, LINC00665 can stabilize AhR protein through the LINC00665/miR-582-5p/UCHL3 regulatory axis, thus promoting the in vivo tumor formation of NSCLC cells and reducing the radiosensitivity." (PMID 35918714, 2022). "Whilst this study did not provide a clear understanding of the potential role of other AhR-induced CYP1 isoforms in breast CSCs, it partially substantiates the involvement of the receptor in regulating the stem cell compartment within the tumour microenvironment." (PMID 33809117, 2021). "Mechanistically, lncRNA-SLCC1 interacted with AHR and transcriptionally activated HK2 expression, the crucial enzyme in glucose metabolism, thereby driving the glycolysis pathway and accelerating CRC tumor growth." (PMID 33602893, 2021). "Concerning NK cells, AHR is involved in the regulation of the plasticity between ILC3 and CD56bright NK cells, the homeostasis of liver-resident NK cells, the anti-tumor response, cytokine production, as well as receptor repertoire expression, including the expression of trafficking receptors." (PMID 33717133, 2021). "Interestingly, AHR is involved in the dormancy of tumor cells in response to IFNG, thus promoting tumor immune evasion." (PMID 34566988, 2021). "As the transcription factor AhR together with IDO1 and TDO2 are present in tumor cells, it has been proposed that KYN could have a dual role in promoting cancer invasion and immune escape." (PMID 34943977, 2021). "Differential AHR levels are commonly found in the comparison of tumor samples from smoking and nonsmoking patients." (PMID 34373448, 2021). "Intratumoral aromatase status was associated with hormone receptor negativity and other aggressive tumor characteristics but not AhR in the current study." (PMID 34094928, 2021).
tumor (continued). "The aryl hydrocarbon receptor (AHR) and hypoxia-inducible factor (HIF)-1α are two transcription factors crucial for cancer development, whose activities are dependent on tumor microenvironment conditions, such as the presence of metabolites from the tryptophan pathway and hypoxia, respectively." (PMID 34572746, 2021). "Additionally, KYNA is an endogenous agonist at the aryl hydrocarbon receptor (AHR), expressed in immune cells and in tumor cells." (PMID 33401674, 2021). "Another small molecule AhR inhibitor—BAY218, used in the murine model—reduced tumor growth and enhanced immune response by increasing the infiltration of CD8+ T and NK cells with simultaneous reduction with regard to suppressive GR1+ myeloid cells and M2 macrophages." (PMID 34071442, 2021). "Importantly, we provide evidence from ex-vivo experiments that tumor antigens modulated by IFN-γ induces IDO, which then promotes antigen-specific Breg differentiation through AhR pathway." (PMID 34867973, 2021). "The IFN-stimulated IDO1/Kyn/AhR cascade is favoured over the JAK/STAT pathway in TRCs rather than in differentiated tumour cells." (PMID 34539663, 2021). "Indeed, the TDO2-kynurenines-AhR axis had an immune regulatory role of restricting the activation of T cells, and TDO2 inhibitor treatment showed recruitment of the anti-tumor effect in mouse models." (PMID 34174844, 2021). "Future studies are needed to evaluate transcript data from patients who have received AI or chemotherapy treatment and it is possible much higher expression of CYPs induced by AhR, CAR and PXR would be noticeable and an important factor to consider in patients with relapsed tumours." (PMID 33809117, 2021). "In this context, AhR and IL24 might be used as composite targets for screening anti-tumor migration compounds in there." (PMID 34955744, 2021). "More importantly, the combination of AhR inhibitor PDM2 and chemotherapy revealed strengthened tumor suppressive effects in subcutaneous tumor-bearing mice, which descried an innovative approach for clinical tumor therapy targeting Trp metabolism." (PMID 34657635, 2021). "Preclinical studies have also suggested that aryl hydrocarbon receptor could become another possible target of the IDO/TDO kynurenine pathway in the treatment of cancer, due to its immunosuppressive role in tumours." (PMID 32270230, 2020). "Since most studies on the effects of AHR agonists in mice have been performed on animals fed a chow diet, it is likely that any resulting PUFA metabolism that occurred was stimulatory towards tumor progression." (PMID 32398692, 2020). "In BC, AHR has been pointed as a potential inductor of carcinogenesis, but its correlation with tumor progression had not yet been demonstrated." (PMID 32907554, 2020). "Tumor repopulating cells (TRCs), a self-renewing, highly tumorigenic subpopulation of cancer cells, highly express IDO1 and transfer kynurenine to CD8+ T cells, which induces programmed cell death protein 1 (PD-1) expression through the kynurenine-AhR pathway." (PMID 32824193, 2020). "Its involvement in tumorigenesis is not well established, but recent studies have shown that AhR can exhibit tumor-specific, pro-oncogenic and tumor suppressor-like functions." (PMID 32085612, 2020). "All analyzed tumor samples showed higher AhR staining compared to adjacent normal thyroid and AhR was clearly detectable in the 2 lymph node metastasis, too." (PMID 31936153, 2020). "As IDO-induced kynurenine inhibits NK cells and CD8+ T cells via AhR activation, this is another route whereby O-GlcNAcylation in MSC, as well as in CSC, may modulate immune suppression in the tumour microenvironment." (PMID 33375613, 2020). "Furthermore, AHR activation and PXR expression related inversely to cancer cell proliferation level and to the stage and grade of the tumor." (PMID 32854297, 2020).
tumor (continued). "Many commonly used pharmaceuticals exhibit AhR activity and several of these compounds including tranilast, raloxifene, leflunomide, OME, and flutamide have been characterized as SAhRMs and inhibited tumor growth." (PMID 32731514, 2020). "The regulatory role ofaryl hydrocarbon receptor (AhR) and its endogenous ligand, 6-formylindolo[3,2-b]carbazole (FICZ) on the expressionof tumor suppressor miRNAs, miR-22, miR-515-5p and miR-124-3p, as well as their association with the estrogenreceptor alpha (ERα) were the aims of this study." (PMID 31606975, 2020). "We also predicted some driver mutations in genes that were not reported to display oncogenic or tumour suppressive properties in BCa, such as AHR Q383H and RREB1 Q392*." (PMID 32988402, 2020). "Actually, AhR protein expresses in most tissues, and increased level and activity of AhR and its nuclear localization have been detected in tumor microenvironment compared with surrounding non-malignant tissues." (PMID 33278884, 2020). "Notably, circadian factors have been relatively little investigated in GBM/GSC and tumour microenvironment cells, contributing to the heterogeneity in GBM/GSC pathophysiology in published studies, including in regard to the AhR." (PMID 35582450, 2020). "While AHR levels frequently correlated with increased tumor aggression, AHR levels per se were understood to not necessarily represent levels of AHR activity." (PMID 33396563, 2020). "Within tumor cells, indoleamine-2,3-dioxygenase (IDO) and tryptophan-2,3-dioxygenase (TDO)-mediated tryptophan catabolism produces the active metabolite kynurenine, an agonist of the aryl hydrocarbon receptor (AhR) that exerts immunosuppressive functions." (PMID 32483452, 2020). "In contrast, treatment with an AHR inhibitor (AHRi1, CH-223191) led to tumor growth inhibition in both B16IDO or B16TDO models, but not B16WT." (PMID 32782249, 2020). "AhR activation in CD8+ T cells and NK cells is one of a number of processes contributing to ‘exhaustion’ in these cells, and thereby to the immune suppression that is evident in the tumour microenvironment of almost all cancers." (PMID 33375613, 2020). "In the tumour microenvironment, CD8+ T cells, NK cells, and γδ-T cell ‘exhaustion’ arises from the release of kynurenine by cancer stem-like cells, which activates the AhR on these immune cells." (PMID 32867244, 2020). "Interestingly, AHR had been shown to cooperate with HIF1α through the commonly shared partner, AHR nuclear translocator (ARNT/HIF1β), to orchestrate glycolysis and tumor microenvironment." (PMID 32226544, 2020). "Here, the authors show that AHR targeting in IDO/TDO-expressing tumours counteracts a regulatory T cell/macrophage suppressive axis and synergizes with immune checkpoint blockade to hinder tumour growth." (PMID 32782249, 2020). "Nevertheless, our results suggest that WT UCHL3, but not UCHL3 mutants, promotes tumor growth and stem-like properties through stabilizing AhR in a DUB activity-dependent manner." (PMID 32546741, 2020). "Furthermore, KYNA acts as a potent endogenous agonist at the aryl hydrocarbon receptor (AHR), a transcription factor in the helix-loop-helix (bHLH) Per/ARNT/Sim family, which is expressed in tumor cells, as well as various cells of the immune system." (PMID 32604956, 2020). "AhR was predominantly expressed in the nuclei of high-grade clear cell RCC (ccRCC) and tumor-infiltrating lymphocytes (TILs), and its expression levels in cancer cells and TILs correlated with the pathological tumor stage and histological grade." (PMID 32443455, 2020). "This AhR-IL-6-STAT3 loop is correlated with a weak prognosis in lung cancer, favoring the idea that IDO-mediated immunosuppression enables the immune evade of tumor cells." (PMID 32957545, 2020). "RACK1 may act via a variety of processes in tumours, including upregulating the assembly and activity of the NLRP3 inflammasome, miRNAs patterning, and AhR regulation." (PMID 33375613, 2020).
tumor (continued). "Expression of AhR and CYP1A1 protein in MKN‐45 tumour tissue was analysed by immunohistochemistry." (PMID 31876059, 2020). "In non-cutaneous tumors, AHR is an established factor that induces suppression of the anti-tumor immune response, resulting in the escape of tumor cells from immune-mediated cell death." (PMID 31552251, 2019). "For these tumor types, five cancer drivers were targeted only by NPs at < 100 nM, including Adenylate Cyclase 1 (ADCY1), Matrix Metallopeptidase 2 (MMP2), Aryl Hydrocarbon Receptor (AHR), Cyclin Dependent Kinase 2 (CDK2), and Mitogen-Activated Protein Kinase 11 (MAP3K11)." (PMID 31214023, 2019). "It is known that the tumor microenvironment is enriched with indoleamine-pyrrole 2,3-dioxygenase (IDO), which metabolizes tryptophan to kynurenine, an endogenous ligand for the aryl hydrocarbon receptor (AHR)." (PMID 31849995, 2019). "In another study, NCOA7 promoted tumor cell proliferation via enhancement of AhR transcriptional activity in the absence of externally added ligands, possibly suggesting that NCOA7 is a ligand-independent coactivator of AhR." (PMID 31481962, 2019). "On the other hand, the mechanism of the AhR Repressor (AhRR) acting as a tumor suppressor is poorly understood and has not been assessed in vivo." (PMID 31035533, 2019). "Notch signaling inhibition reduced the IL-22 production by CD4+ T cells from tumor site, and this process was accompanied by down-regulation of AhR mRNA expression, but not RORγt." (PMID 30473538, 2018). "The role of the AhR in tumor immunity has not been explored in depth and merits further investigation." (PMID 29487603, 2018). "In fact, tumor growth significantly increased total liver weight in AhR-null but not in wild type mice." (PMID 28874739, 2017). "In this study, we provide evidences that suggest a plausible mechanism linking AHR and HCC via targeting of HDAC8, which promotes tumor cell growth and may restrain the expression of RB1 tumor suppressors in HCCs." (PMID 27283490, 2017). "Over-expression of AHR in GH3 cells revealed a tumour suppressor potential independent of exogenous ligand activation by benzo α-pyrene (BαP)." (PMID 28649092, 2017). "In contrast, no tumour formation was observed from cells overexpressing AhR alone and combined with BafA1 treatment." (PMID 28195146, 2017). "Protein analysis of tumors growing in AhR+/+ mice revealed a marked downregulation of AhR expression in the tumor proper (T) as compared to surrounding non-tumoral tissue (NT) from the same livers." (PMID 28874739, 2017). "Moreover, in vivo tumour metastasis was assessed using wt-A549, and shAhR-A549, wt-CL1-5, and AhR-overexpressing CL1-5 cells by intravenous tail vein injection into mice." (PMID 28195146, 2017). "Based on these observations, we present and discuss here the hypothesis that HCV infection promotes HCC by modulation of the TDO–Kyn–AhR pathway, resulting in tumorigenesis as well as in suppression of both anti-HCV and anti-tumour immune responses." (PMID 27867514, 2016). "Whether similar tumour-promoting interactions occur with KYN and AhR in BrCa remains unknown but are likely." (PMID 26646699, 2016). "In the liver, the AhR appears to function as tumor suppressor gene in the absence of its toxic ligands, whereas its aberrant long-term activation induces liver carcinogenesis." (PMID 27274734, 2016). "Also, germ-free AhR (−/−) and AhR (−/−)/ASC (−/−) mice had reduced tumor formation compared with AhR (−/−) mice." (PMID 26264025, 2015). "In contrast, there was no global upregulation of the AhR target genes in tumour spheres comparing with their parental cells." (PMID 26059097, 2015). "In contrast to the POU5F1, the correlations between the AHR mRNA level and the tumour volume/tumour weight were not significant in the vehicle group but remarkably increased in the ITE group." (PMID 26059097, 2015).
tumor (continued). "Studies in animal models of CRC suggest that in the basal state without xenobiotic ligands AhR acts as a tumor suppressor, particularly in cecal tumors." (PMID 26264025, 2015). "Interestingly, the promoter activity of aurora C, which confers tumor growth during tumorigenesis, was further increased in cells that co-expressed ARNT and AhR." (PMID 25839165, 2015). "Translated into the clinic, the non-genomic control of IDO1 by activated AhR becomes of great interest in neoplasia." (PMID 25360135, 2014). "Recently, several papers reported that the AhR gene can act as a tumor suppressor in the absence of xenobiotics." (PMID 23656719, 2013). "Endogenous AhR that is not activated by exogenous ligand has, in general, pro-proliferative and tumor-promoting properties." (PMID 20565777, 2010). "Mechanistically, receptor crosstalk between the aryl hydrocarbon receptor (AhR) and the estrogen receptor (ER) triggers mitochondrial dysfunction and inhibits ten-eleven translocation (TET) enzyme activity, creating an oxidative state that establishes epigenetic locking of tumor suppressor genes." (PMID 41822350, 2026). "For instance, Trp catabolism not only produces Kyn that binds to TAM AhR to induce M2-like TAM polarization, but also activates GCN2 via Trp depletion to promote M2-like TAM polarization and suppress CD8+ T cell proliferation, further enhancing tumor cell immune evasion." (PMID 41281760, 2025). "Notably, this study identifies TOX as an oncogenic factor in non-immunological contexts and underscores AHR's tumor-suppressive function through TOX repression, offering novel insights into the mechanisms underlying As3+-induced carcinogenesis." (PMID 40303305, 2025). "In conclusion, HMP1G NPs downregulated tumor‐derived IDO1 the AhR/STAT3/IL axis, improving KYN/TRP metabolism dysregulation, effectively overcoming metabolic immune suppression within the TME, reversing immunological tolerance in cold tumors, and sensitizing tumor cells to ICB therapy." (PMID 39661740, 2025). "Hence, it is conceivable that the proteasomal degradation of AhR triggered by its activation, rather than the activation per se, facilitated tumor immunogenicity." (PMID 40583248, 2025). "Therefore, KYNA, as a ligand of AhR and GPR35, may indirectly affect immune balance and be involved in tumor immune escape." (PMID 40650047, 2025). "But regardless of the mechanism, the activation of AhR induces CD39 expression in tumor-associated cells, promotes CD8+ T-cell dysfunction, and promotes Treg cell proliferation to induce immunosuppression, thereby enabling the tumor microenvironment." (PMID 41282989, 2025). "Several studies demonstrated that the AhR is transcriptionally active in malignant cells in the absence of environmental ligands through tumor production of endogenous AhR ligands, at least some of which are likely to be derived from the kynurenine (Kyn) pathway of tryptophan metabolism." (PMID 40449595, 2025). "Although PARP7 and AHR expression levels as well as an intact STING signalling pathway will be needed to target PARP7-AHR-IFN signalling for cancer treatment, identifying which cancer cells or tumours will respond to such interventions will still require the identification of robust biomarkers." (PMID 41432900, 2025). "The observed co-expression of IDO2 and AhR, and the absence of associations between AhR and IDO1 or TDO2, may indicate a shift toward IDO2–AhR–driven immune suppression in advanced tumours." (PMID 40471422, 2025). "Under normoxic conditions, tumor cells maintain vascular homeostasis through baseline levels of VEGF, while hypoxic conditions significantly increase angiogenic capacity by activating both the hypoxia-inducible factor (HIF) pathway and the aryl hydrocarbon receptor (AhR) pathway." (PMID 40438141, 2025).